IL2 (interleukin 2)
Diseases named in the same sentence as IL2 in open-access papers (continued):
Sharing a sentence is not in itself a finding about the gene and the disease.
cancer (continued). "As to cytokine release by CD8+ cells, we focused on TNF-α and IL-2, cytokines usually associated with cancer eradication." (PMID 34199263, 2021). "Differences in the cytokine profile showed that IL-2 and IL-10 present a near-significant association with the cancer relapse." (PMID 32013102, 2020). "Overall, cytokines are divided into proinflammatory groups such as TNF-α, IL-1β, IL-2, and IL-6, which play a role in initiating chronic inflammation and activating the NF-κB pathway and are strongly linked to cancer growth." (PMID 32156252, 2020). "As far as BCG-therapy associated limitations are concerned, the importance of IL-2 as a candidate for cancer immunotherapy is becoming even more significant." (PMID 33027905, 2020). "Severe adverse events and preferential expansion of immunosuppressive Treg cells limit the therapeutic use of recombinant IL-2 in cancer; these drawbacks are potentially associated with signals through the high-affinity receptor complex." (PMID 33266177, 2020). "We believe that using FSD13 to treat cancer patients will accomplish at least the same remission rate as IL-2 but with much lower risk of any significant side effects." (PMID 30250191, 2018). "IL-2 therapy can lead to durable responses in cancer patients but it is associated with significant toxicity and even life-threatening syndromes." (PMID 30619269, 2018). "Recent reports suggested that most of the pro-inflammatory cytokines, including IL-2, IL-6, IL-1β and IL-10, are over-expressed at cancer specific sites and particularly linked to invasion and progression of sever HCC conditions." (PMID 29651140, 2018). "High dose IL-2 is a viable treatment option for cancer immune therapy, but the underlying mechanism for the accompanying undesirable morbidity is unclear." (PMID 29176694, 2017). "An increased Th1/Th2 ratio (IL-2/IL-4) is associated with the activation of cell-mediated immunity and would be potentially beneficial for pathogen or cancer elimination, while a decreased ratio would raise the risk of inflammation progression." (PMID 27830496, 2016). "The TGFβ pathway is exquisitely involved in T-cell autoimmunity and has been linked with HT for some time, as treatment of cancer patients with IL-2, a downstream target of the pathway, resulted in increased incidence of HT." (PMID 22969748, 2012). "In this study, autologous peripheral blood T cells were pre-cultured in medium supplemented with CD3-specific antibody and IL-2, and cell infusion was shown to reduce the risk of cancer recurrence by 41% when compared to a control group receiving only surgery." (PMID 19272130, 2009). "More concerning is the possible connection between IL-2 and cancer risk." (PMID 40804870, 2025). "Furthermore, the KRAS signaling pathway, IL6/JAK/STAT3 pathway, and IL-2/STAT5 pathway were strongly linked to STX7 expression in cancer." (PMID 40999361, 2025). "High-dose IL-2 is associated with increased infection risk in cancer patients." (PMID 41550947, 2025). "Furthermore, IL-2 has been encoded in oncolytic viruses (OV) that are delivered intratumorally and preferentially replicate in cancer cells." (PMID 39114660, 2024). "This could be a cause of the deficient immune response to cancer cells, a deficiency that can be restored using IL-2 therapies." (PMID 39404425, 2024). "Moreover, lastly, what is the potential of IL-2 and IL-2R as diagnostic, prognostic, or predictive markers for cancer?" (PMID 37516849, 2023). "Moreover, MSC(AT)s were engineered with lentivirus encoding interleukin 2 (IL-2), a cytokine that stimulates anti-cancer immunity, for its EV-mediated delivery, aiming to reduce systemic toxicity." (PMID 37189850, 2023). "Such IL-2 variants provide an effective, yet less toxic means of cancer immunotherapy." (PMID 35213635, 2022). "The level of IL-2 was negatively associated with tumor size in HPV-induced cancer model." (PMID 36726985, 2022). "IL-2, a typical cytokine therapy, can cause the patient’s cancer to subside." (PMID 36532065, 2022).
cancer (continued). "Interleukin-2 was one of the earliest immunotherapy treatments, but the significant disadvantages associated with systemic IL-2 treatment have led to more sophisticated versions, capable of targeting the cancer." (PMID 34168629, 2021). "In contrast, the expression of genes regulating immune cell trafficking (e.g., CXCL13, CXCL9, XCL2, CCL5), T-cell activation and clonal expansion (e.g., CD27, CD28, ICOS, IL21, IL2) were massively decreased in 9p21-loss tumors across multiple cancer types/subtypes." (PMID 34556668, 2021). "However, vascular leak syndrome, hypotension, and liver toxicities associated with HD IL-2 have limited its use in cancer immunotherapy." (PMID 32005826, 2020). "In selected patients, cetuximab could be managed as an “immunotherapeutic drug” and association with NK-activating cytokines (IFNs, IL-2) could also gain relevance in the attempt to activate ADCC against antibody-coated cancer cells." (PMID 31500586, 2019). "This variant induced T cell proliferation more potently than wt IL-2, suggesting that it could be a better alternative than wt for cancer immunotherapy since lower doses of the variant would be required to show efficacy which could result in lower toxicity." (PMID 30319612, 2018). "IL-2 is used systemically for cancer therapy but it is associated with severe toxicity." (PMID 30410056, 2018). "The pro-inflammatory cytokine mediators include tumor necrosis factor-alpha (TNF-α), interferon alpha (IFN-α), interleukin-2 and -8 (IL-2 and IL-8), causing inflammation and contribute to cancer development, primarily by causing oxidative stress and DNA damage." (PMID 30607173, 2018). "Furthermore, increased inhibitory receptor expression was associated with reduced IFN-γ and increased IL-2 production by bacterial antigen-specific CD8+ T cells in the cancer group." (PMID 24796533, 2014). "Furthermore, IL-2 is used as treatment for certain cancers, which is documented to result in an increased risk of HT." (PMID 22969748, 2012). "This study shows that low-dose IL-2 immunotherapy of cancer may stimulate the in vivo release of IL-12, and it would suggest that IL-2-induced IL-12 enhancement is associated with a favourable prognosis." (PMID 9667674, 1998). "Evidence describing the immunomodulating effects of LDN and its impact on the synthesis and modulation of signaling pathways associated with IL-2 supports the hypothesis that IL-2+LDN immunotherapy may provide therapeutic benefits in cancers showing increased expression of OGF and OGFr." (PMID 38539570, 2024). "Another essential aspect to evaluate later would be the expression of CD95, CD95L, IL-2, and IL-2R in other types of cancer associated with the presence of HPV to determine whether these molecules are present and whether they are involved in cell proliferation." (PMID 39766250, 2024). "Indeed, it has been hypothesized that contrary to some RCC patients, the expression of IL-2 and the heterotrimeric IL-2Rαβγ complex is associated with cancer malignancy, as shown in breast cancer." (PMID 38893211, 2024). "Interestingly, HD IL2-associated vessel toxicity can be used as a treatment for cancer." (PMID 32560387, 2020). "Moreover, immunotherapies such as interleukin-2 (IL-2), adoptive cell transfer, and antibodies targeting cytotoxic T-lymphocyte–associated antigen 4 or programmed death 1 receptor (PD-1) seem promising for treating cancers." (PMID 31694582, 2019). "For example, IL-2 and GM-CSF have been investigated in combination with other immunotherapeutic strategies, such as immune checkpoint inhibitors and cancer vaccines." (PMID 41355950, 2026). "When recombinant IL-1 is incubated in vitro in the presence of other cytokines, such as IFN and IL-2, it increases the cancer cell killing capacity." (PMID 41596472, 2026). "They reported that both CU‐3 and Compound A increased IL‐2 production in T cells and provoked cell death in melanoma and several other cancer cells." (PMID 40859612, 2026).
cancer (continued). "IL-2 mediates its therapeutic effects by interacting with the β and γ receptor subunits against cancer, whereas interaction with the α, β, and γ receptor complexes is critical for treating autoimmune disorders." (PMID 41835540, 2026). "The use of engineered probiotics to deliver cytokines, such as interleukin-2 (IL-2) and granulocyte-macrophage colony-stimulating factor (GM-CSF), has gained significant attention in recent years as a promising approach in cancer immunotherapy." (PMID 41355950, 2026). "Interleukin-2 (IL-2) remains an attractive cytokine for enhancing antigen-specific CD8 T-cell responses in cancer immunotherapy, but systemic toxicity hinders its broad clinical application." (PMID 42294879, 2026). "An important consequence of controlling JAK/STAT pathways is the attenuation of interferon-γ (IFNγ) and interleukin-2 (IL-2) signaling, which can impair the recognition and elimination of cancer cells by T cells." (PMID 41302504, 2025). "In this phase I trial, 13 patients with advanced cancer were treated with five dose levels of IL-2 mutein, from 300 to 2400 IU/kg." (PMID 40486521, 2025). "The safety of such approaches requires careful oversight, as it is likely that hyperactivity of peripheral NK cells contributes to severe adverse events in human cancer patients treated with high-dose IL-2." (PMID 40410571, 2025). "Due to itsimmunoregulatory properties, IL-2 has been extensively studied as a therapeutictarget for cancer and autoimmune diseases." (PMID 39801407, 2025). "IL-2 is a key cytokine in cancer surveillance, is involved in innate and adaptive immunity, and plays a pivotal role in the proliferation of natural killer (NK) cells and T lymphocytes." (PMID 40568585, 2025). "Even though IL2 monotherapy was not as successful as expected in improving patient survival, the combination therapy of IL2 and other anti-cancer agents showed encouraging clinical results, especially in combination with peptide cancer vaccines." (PMID 41050655, 2025). "Among cytokines implicated in the pre-cancer and initiation of HCC, the proinflammatory cytokines MCP-1, IL-2 and IL-12p70 were significantly secreted in obese individuals compared to their non-obese counterparts." (PMID 41219858, 2025). "NL-201 by Neoleukin Therapeutics, a de novo protein mimicking IL-2 and IL-15, reached Phase 1 trials for cancer before discontinuation in 2022." (PMID 40155973, 2025). "The targets for the drugs used in various cancers include cytokines (e.g., aldesleukin – an interleukin-2 blocker) as well as tumor growth factors (e.g., sargramostim – a GM-CSF blocker)." (PMID 40766321, 2025). "Currently, many clinical trials are carried out in parallel to characterize possible contributions to cancer treatment of autologous or allogeneic γδ T cells partly stimulated with zoledronate, interleukin-2 (IL-2), or vitamin C or D." (PMID 39941030, 2025). "Since the discovery of interleukin-2 (IL-2) in 1976 as a powerful T cell growth factor, it has attracted considerable interest as a potential cancer therapy." (PMID 41584608, 2025). "The ability to modulate immune responses precisely, coupled with the integration of IL-2 immunocytokines into tailored treatment strategies, has the potential to redefine cancer therapy." (PMID 39852848, 2025). "XmAb808 promoted IFNγ release from T cells and IL2-mediated expansion of T cells with enhanced survival, translating to increased T cell–mediated killing of cancer cells in vitro but only in the presence of both Signal 1 and B7-H3+ target cells." (PMID 39301613, 2025). "• CD39+ and CD73+ EVs.• Spread of EVs to TDLN and metastatic sites.• IL-2 is available to both CD8 and Treg for their expansion.• MTAP loss variant cancers bypass direct A2AR antagonist blocking." (PMID 41583489, 2025). "Unfortunately, many cytokines for cancer immunotherapy, such as IL-2 and IL-12, demonstrate poor intrinsic retention upon i.t. administration largely due to their small size." (PMID 40404625, 2025).
cancer (continued). "Beyond established IL-2-based therapies, invikafusp alfa (also known as STAR0602) introduces an innovative application of IL-2 in cancer immunotherapy." (PMID 40508202, 2025). "Conversely, skimmianine-mediated TNF-α suppression reduced cancer progression, yet TNF-α-associated hub proteins (TNF-α, IL2, MMP9) remained positively correlated with immune infiltration, highlighting the dual role of TNF-α in the TME." (PMID 40430573, 2025). "Tregs suppress immune response in different types of cancer, and MCs interact with Inducible T-cell co-stimulator (ICOS)+ Tregs through IL-33 and IL-2 and promote cancer progression." (PMID 41425713, 2025). "Insufficient efficacy combined with its considerable toxicity has thus prevented widespread use of IL-2 in cancer treatment." (PMID 40789741, 2025). "The combination of IL-2-loaded liposomes with immunostimulatory agents enhances immune responses, offering promising potential for cancer immunotherapy." (PMID 40143046, 2025). "The curative effect of IL2 in cancer treatment is dose-dependent, but the main challenge of IL2 in terms of its use as a cancer immunotherapy was that it affects both CD8+ T cells and CD4+Foxp3+ Tregs." (PMID 41050655, 2025). "mTOR inhibitors not only suppress these oncogenic processes but also inhibit T-cell activation and proliferation by downregulating IL-2 production, making them effective as both immunosuppressive and anti-cancer agents." (PMID 40098014, 2025). "Recent study marked miR-215-5p and miR-375 micro RNAs, found to be highly expressed in CD4+ derived EVs after IL-2 stimulation, as capable of dampening cancer cell growth via direct increase of CD8+ T cell cytotoxic activity." (PMID 39961904, 2025). "Many studies tried to evaluate the correlation between cytokines and the pathogenesis of various cancer types and IL-2, IL-6, IL-10, and TNF-α are often target of these analyses." (PMID 40869161, 2025). "Our findings support the temporally optimized use of CD25-biased IL-2-based therapeutics in combination with ICIs for cancer immunotherapy." (PMID 40789741, 2025). "Similar to the role of IFN-γ, IL-2 has also been demonstrated to play a significant role in the development of cancer-related fatigue." (PMID 39980555, 2025). "Radiotherapy (RT) can stimulate anti-cancer T cell responses, and cytokines, notably interleukin-2 (IL-2), are necessary for optimal T cell function and memory." (PMID 40502703, 2025). "Additional anti-cancer pathways suppressed by PT (i.e., enriched in MA alone) included adipogenesis, IL2/STAT5, cholesterol homeostasis, estrogen response late, UV radiation upregulated genes, and apical junction." (PMID 40227411, 2025). "IL-2 causes an increased release of IFN-γ and TNF-α and the development of CD8+ T-cells, and both are necessary to attack cancer cells." (PMID 40806447, 2025). "Most recently, IL-2 agonist linked to anti-PD1 monoclonal antibody allowed for IL-2 targeting of exhausted T cells in LCMV and cancer mouse models with reduced dosing, presumably allowing for safer treatment." (PMID 40740767, 2025). "Interleukin-2 therapy represents a promising strategy in cancer immunotherapy, with several IL-2 compounds developed to target the IL-2 receptor to enhance immunologic efficacy." (PMID 40698080, 2025). "Systemic administration of recombinant cytokines, such as interferon-α (IFN-α) and interleukin-2 (IL-2), is a clinically proven therapeutic strategy for the treatment of cancer." (PMID 39742319, 2025). "XmAb808 avidly bound cancer cells and stimulated IL2 and IFNγ secretion from T cells cocultured with cancer cells engineered to deliver Signal 1 to T cells via a surface-expressed anti-CD3 antibody." (PMID 39301613, 2025). "While this is a topic for future research, a more multifaceted approach for targeting macrophages and IL-2 should be developed to combat cancer cells more effectively than current methods." (PMID 40666494, 2025).
cancer (continued). "IL‐2 has been approved for cancer immunotherapy and is being investigated for chronic viral infections." (PMID 41190418, 2025). "Stroma-targeted stimulation of the IL2 pathway in these unresponsive tumors restores the anti-cancer efficiency of trastuzumab." (PMID 39981243, 2025). "A previous preclinical study on cancer vaccines genetically engineered to produce native IL-2, showed that optimal protection occurs at medium IL-2 levels, while lower levels reduce treatment success." (PMID 40486521, 2025). "Biolojic Design’s AU-007, targeting IL-2 to enhance cancer immune responses, is currently undergoing trials." (PMID 40155973, 2025). "Herein, we report a sophisticated cRNA-based IL-2 therapy by incorporating immunomodulatory LNPs and hydrogel for potent cancer immunotherapy with alleviated side effects." (PMID 40009662, 2025). "This study provides several important conceptual and translational advancements in the field of IL-2-based cancer immunotherapy." (PMID 40789741, 2025). "While systemic IL-2 administration for cancer has resulted in toxicity, local application, particularly intratumoral administration, shows promise." (PMID 39852848, 2025). "Nevertheless, systemic delivery of IL-2 for cancer therapy presents several significant challenges, including severe non-specific toxicities and the activation of regulatory T cells." (PMID 41041051, 2025). "Cytokines are mediators and modulators of the innate and adaptive immune systems, and immunotherapy based on cytokines such as interferon and interleukin-2 (IL-2) has been used in the treatment of cancer as early as the end of the 20th century." (PMID 40510353, 2025). "IL-2 is a cytokine that can be combined with cancer vaccines to improve the treatment of human malignancies." (PMID 40837119, 2025). "Originally developed as a tuberculosis vaccine, BCG enhances IL-2 expression following intravesical administration, where it attaches to and is internalized by cancer cells." (PMID 40699676, 2025). "In phase I/II, RO7284755, an IL-2 variant immunocytokine connected with an anti-programmed cell death (anti-PD1) moiety, is tested for safety and anti-cancer efficacy (NCT04303858)." (PMID 40584290, 2025). "Another study noted that treatment-resistant tumors harbor specific TGF-beta-activated cancer-associated fibroblasts (CAF), which are associated with low IL-2 activity." (PMID 39981243, 2025). "The interleukin-2 (IL-2) cytokine family, including IL-2, IL-4, IL-7, IL-9, IL-15, and IL-21, plays a vital role in modulating immune responses and has been extensively studied across a range of cancers." (PMID 40636453, 2025). "During cancer progression, T cell responses gradually lose functionality, with interleukin-2 (IL-2) production being among the first effector functions to be impaired." (PMID 40076932, 2025). "The integration of IL-2 immunocytokines into cancer therapy represents a significant advancement, addressing many of the challenges associated with traditional high-dose IL-2 treatment." (PMID 39852848, 2025). "IL-2 has demonstrated moderate efficacy in these cancers, with complete response (CR) rates of 9.3% and 4%, respectively, and a significant portion of these CRs has been long-term durable remissions." (PMID 40789741, 2025). "DSPS can promote the proliferation of T lymphocytes in cancer patients by regulating the expression of cytokines (such as IL-2, IL-4, IL-6, IFN-γ)." (PMID 40867887, 2025). "Suppressing unregulated inflammatory cytokines (IL-2 and TNF-α) and NO productions from macrophages is one method that can reduce the risk of cancer initiation." (PMID 40022126, 2025). "This dual role of IL-2 highlights the need for a balanced immune response to effectively fight cancer and avoid immune suppression." (PMID 41376630, 2025). "Early prospective trials have found that Zoledronate combined with IL-2 can effectively activate Vγ9Vδ2 T cells in vivo and inhibit various malignant tumors." (PMID 39995672, 2025).